IGF2BP2 (insulin like growth factor 2 mRNA binding protein 2)
Diseases named in the same sentence as IGF2BP2 in open-access papers (continued):
Sharing a sentence is not in itself a finding about the gene and the disease.
tumor (continued). "Subcutaneous tumorigenesis experiments in mice showed that knockdown of IGF2BP2 contributed to a decreased tumor size and tumor weight, showing its significant ability in tumor formation." (PMID 35908253, 2023). "The tumor‐promoting effect of IGF2BP2 and its co‐expression with B3GNT6 were verified in an animal model." (PMID 35908253, 2023). "IGF2BP2 has been shown to increase resistance of cancer cells against different drugs in different tumor types." (PMID 37248468, 2023). "Through IHC staining, we observed that IGF2BP2 was located in both cytoplasm and nucleus of tumor cells." (PMID 35773744, 2022). "Several cancer-promoting and inflammation-related functions have been proposed for IGF2BP2, including the promotion of tumor growth and induction of macrophage polarization." (PMID 36246622, 2022). "Expression levels of YTHDF1 and IGF2BP2 were also compared between tumor tissue and normal tissue, and we found that both of them were higher expressed in tumor tissue." (PMID 35646049, 2022). "Meanwhile, compared with IGF2BP1 and IGF2BP3, IGF2BP2 expression exhibited striking intra- and inter-tumor heterogeneity." (PMID 36686749, 2022). "At first, people’s understanding of IGF2BPs was limited to its widespread and high expression in embryos and tumor tissues, and IGF2BP2 is even closely related to metabolic diseases." (PMID 36237306, 2022). "This study confirmed that the expression of IGF2BP2 was significantly increased in OSCC tumor tissues after combining TCGA and GEO datasets, Oncomine, and clinical samples." (PMID 35129592, 2022). "Collectively, these results indicate that IGF2BP2 is involved in the tumor and immune-related KEGG pathway." (PMID 35129592, 2022). "Results obtained in the present study revealed the potential role of IGF2BP2 in tumor immunology and its prognostic value, which will help in elucidating its possible mechanism in OSCC." (PMID 35129592, 2022). "In this study, we also revealed that elevated IGF2BP2 expression was significantly related to tumor size, TNM stage, lymph node metastasis, and depth of invasion." (PMID 36358799, 2022). "The role of IGF2BP2 in tumor prognosis was elucidated in terms of the relationship between IGF2BP2 expression and the overall survival of OSCC patients." (PMID 35919812, 2022). "Results showed a significantly higher expression of IGF2BP2 in OSCC tumor samples than in non-tumor samples in GSE31056, GSE42743, GSE51010, and TCGA datasets (P<0.001)." (PMID 35129592, 2022). "We found that the injection of SiHa cells expressing shIGF2BP2 or shHPV16 E6/E7+oe-NC reduced the tumor size to a similar degree, whereas tumor size was slightly increased in animals injected with shHPV16 E6/E7+oe-IGF2BP2-expressing SiHa cells." (PMID 35002506, 2022). "In terms of tumor immune infiltration, IGF2BP2 was found also negatively correlated with immune infiltration." (PMID 36281789, 2022). "The expression levels of METTL3 and IGF2BP2 were also significantly decreased in RCC tumor tissues compared to normal tissues." (PMID 36591524, 2022). "IGF2BP2 expression was higher in CC tissues than in adjacent tissues and was positively correlated with tumor stage." (PMID 35002506, 2022). "The GSEA results showed that cell apoptosis-, tumor-, and immune-related pathways were significantly enriched in samples with high IGF2BP2 expression." (PMID 35129592, 2022). "Elevated IGF2BP2 expression in OSCC cells has been linked to cell proliferation, metastasis, and tumor-infiltrating immune cells in in vitro experiments." (PMID 35919812, 2022). "RT-qPCR analysis of mRNA levels in 10 OSCC tumor tissues revealed that the mRNA levels of IGF2BP2 was also negatively correlated with that of CD8A." (PMID 35299748, 2022). "Accumulating lines of evidence show IGF2BP2 as upregulated in multiple human cancers and suggest its important role in tumorigenesis and tumor progression." (PMID 36257938, 2022).
tumor (continued). "Consistent with the results of Western blotting, the IHC of excised tumors after imaging also demonstrated high expression of IGF2BP2 in tumor tissues." (PMID 36364436, 2022). "CDC25C, FOXM1, MCM3, MCM7 and many other key genes regulated by IGF2BP2-mediated RNA N6-methyladenosine are related to a variety of immune cell infiltration and tumor purity, and play an important role in the prognosis of hepatocellular carcinoma." (PMID 35129592, 2022). "Western blotting of the patient-derived tumor tissue also showed that IGF2BP2 expression was relatively higher in tumor tissue than in paracancerous tissue." (PMID 36364436, 2022). "One study reported that overexpression of IGF2BP2 can promote glycolysis and stimulate tumor cell proliferation, thereby affecting the occurrence and development of tumors." (PMID 35129592, 2022). "Based on the TCGA database, IGF2BP2 was evidently downregulated in RCC tumour samples compared to normal samples." (PMID 36591524, 2022). "Further studies revealed that the key regulatory network of the m6A methylation reader, IGF2BP2, stabilizes lncRNA and collectively contributes to mitochondrial energy metabolism in tumor pathogenesis." (PMID 35794625, 2022). "ShHPV16E6/E7+oe-NC and shIGF2BP2 attenuated tumor weight, whereas shHPV16 E6/E7+oe-IGF2BP2 increased the tumor weight." (PMID 35002506, 2022). "The upregulation of IGF2BP2 has also been shown to promote OSCC progression associated with cell proliferation, metastasis, and tumor-infiltrating immune cells." (PMID 35919812, 2022). "Further, we found that gene expression of MMP9 and IGF2BP2 was positively correlated with levels of several APCs, which processed tumor antigens and presented them to CD8+T cells." (PMID 36569935, 2022). "IGF2BP2 dysregulation is frequently observed and plays a key tumor-promoting role in various malignancies, especially in CRC." (PMID 35773744, 2022). "Overexpression of IGF2BP2 can promote tumor cell proliferation, stimulate migration and invasion, inhibit cell apoptosis, and accelerate tumor progression." (PMID 35129592, 2022). "TISIDB showed that the high expression of IGF2BP2 in pan-cancer tended to be accompanied by a higher tumor grade and cancer stage." (PMID 36281789, 2022). "The expression of IGF2BP2 was negatively correlated with 28 tumor-infiltrating lymphocyte (TIL) types generally in TISIDB." (PMID 36281789, 2022). "Functioning as a tumor promoter, IGF2BP2 is significantly upregulated in EC tissues and is considered to be associated with poor prognosis." (PMID 36364436, 2022). "Combined with our data, the RNA‐seq results revealed that the expression of IGF2BP2 was significantly decreased in RCC tumour tissues." (PMID 35678231, 2022). "The RT-qPCR analysis demonstrated that IGF2BP2 was significantly overexpressed in HNSCC tumor samples compared with NATs." (PMID 34980207, 2022). "The CIBERSORT method was applied to confirm the association between IGF2BP2 expression and the immune component through constructing 21 types of immune cell profiles in OSCC cases and analyzing the proportion of tumor-infiltrating immune subtypes." (PMID 35129592, 2022). "Antibody HPA035145 staining for IGF2BP2 in normal kidney tissue was low, whereas it was medium in tumor tissue." (PMID 34420511, 2022). "Further examination revealed that circITGB6 induced macrophage polarization toward the pro-tumor M2 phenotype through the direct interaction with IGF2BP2 to stabilize FGF9 mRNA." (PMID 36428803, 2022). "GSEA results showed that apoptosis -, tumor - and immune-related pathways were significantly enriched in IGF2BP2 highly expressed samples." (PMID 36237306, 2022). "Regarding IGF2BP2, it was upregulated in HCC patients compared to healthy controls, and IGF2BP2 expression was positively associated with decreased tumor differentiation and increased size, metastasis and portal vein infiltration in HCC." (PMID 34692544, 2021).
tumor (continued). "Recent studies also confirm that IGF2BP2 participates in the regulation of tumor cell proliferation by regulating signaling pathways in tumor development and development." (PMID 34345216, 2021). "It was observed that the growth rate of xenograft tumors and the tumor weight on the 35th d were significantly suppressed by IGF2BP2 silencing but restored after circ_0000745 overexpression." (PMID 34774079, 2021). "Taken together, the results demonstrated that inhibition of IGF2BP2 or PD-L1 expression reduced tumor growth." (PMID 34608837, 2021). "In vivo, the tumor volume and weight were reduced by both the PD-L1 inhibitor and IGF2BP2 knockdown." (PMID 34608837, 2021). "Meanwhile, Ccn6, secreted by normal breast epithelium, can suppress the expression of IGF2BP2 protein in cancerous breast tissues, thus modulating the growth of the tumor." (PMID 33568150, 2021). "The relative proportions of IGF2BP2 in different sCNA states in all tumor types are shown as a stacked bar chart." (PMID 33816266, 2021). "In comparison with IGF2BP2-Wt group, transplanted tumor size in IGF2BP2-3KR group was significantly reduced, whereas survival time of nude mice was significantly prolonged." (PMID 34345216, 2021). "In tumour cells, IGF2BP2 expression is upregulated, which increases the opportunity for IGF2PB2 to interact with DANCR and stabilize it, especially when the RNA methylation mechanism is dysregulated." (PMID 34246319, 2021). "Ectopic expression of miR-138 suppresses cell proliferation, invasion, and xenograft tumor formation, by directly repressing IGF2BP2 expression." (PMID 33611339, 2021). "This explanation is consistent with previous data showing that the lncRNAs LINRIS and GLCC1 promote tumor growth by inhibiting the degradation and enhancing the stability of oncogenic proteins IGF2BP2 and c-MYC, respectively." (PMID 33668685, 2021). "CTNNB1 expression positively correlated with both m6A writers and IGF2BP2 in 38 paired CCA tumor and adjacent normal tissues, which was further validated by data sets in TCGA database." (PMID 34347395, 2021). "Subsequently, IGF2BP2 knockdown- H1299/R cells were subcutaneously injected into BALB/C nude mice for tumor formation (n = 7)." (PMID 34630126, 2021). "Expression of IGF2BP2 also promotes tumor progression by inducing epithelial-mesenchymal transition (EMT)." (PMID 33568150, 2021). "Subsequently, the RT-qPCR results confirmed an upregulation of IGF2BP2 in the OC tumor tissues relative to the adjacent tissues, presenting a positive correlation with circ_0000745." (PMID 34774079, 2021). "The reports above fully confirm that IGF2BP2 plays an essential role during the complicated tumor progression process." (PMID 34345216, 2021). "Then we established the subcutaneous tumor bearing nude mice model to better understand the oncogenic role of IGF2BP2 in NSCLC." (PMID 35111811, 2021). "After determining the malignant hallmarks of IGF2BP2, the relationship between IGF2BP2 expression and tumor immune cell infiltration in cancers was explored." (PMID 33816266, 2021). "As the results presented, in comparison to IGF2BP2-Wt group, the tumor volumes were significantly lower in IGF2BP2-3KR group." (PMID 34345216, 2021). "IGF2BP1 was increased in MNA tumours, whereas in 4S disease (the possibly tumour suppressive) IGF2BP2 was the most up-regulated family member." (PMID 32707690, 2020). "The results revealed that METTL3 and IGF2BP2 were significantly upregulated in tumor tissues compared with those in adjacent normal tissues." (PMID 33224879, 2020). "As compared to normal tissue, IGF2BP2 was significantly upregulated in tumor tissue at the protein level and this upregulation of IGF2BP2 was an unfavorable marker for cancer patients." (PMID 31804607, 2020). "In tumor cells, IGF2BP2 is upregulated, which increases the chance of IGF2PB2 to interact with and stabilize DANCR, especially, when RNA methylation machinery is dysregulated." (PMID 31804607, 2020).
tumor (continued). "Tumor tissues from knockdown IGF2BP2 mice showed lower levels of KI-67, as compared to control mice." (PMID 33224879, 2020). "We discovered that the copy number of IGF2BP2 in tumor tissues was higher than that in adjacent normal tissues." (PMID 33224879, 2020). "We found a high expression of IGF2BP2 in HNSCC tumor tissues and verified this result in our laboratory using immunohistochemistry." (PMID 32391379, 2020). "Consistent with results in tumor tissue, the IGF2BP2 expression was significantly up-regulated in HCC cell lines." (PMID 33224879, 2020). "We analyzed the differences in the expression of IGF2BP2 between HNSCC tumor tissues and adjacent tissues through differential expression scatter plots and paired difference analyses." (PMID 32391379, 2020). "Among all of these genes, only IGF2BP2 had significantly higher expression pattern and distinguishable protein expression in tumor tissue compared to normal tissue." (PMID 32514248, 2020). "Especially IGF2BP2 (Insulin-like growth factor 2 mRNA binding protein 2), which was most significantly overexpressed in tumor tissue." (PMID 32514248, 2020). "Experiments with IGF2BP2 knockout (KO) mice demonstrated that IGF2BP2 is a tumor promoter that drives cancer progression." (PMID 31804607, 2020). "Analysis of TCGA data and IHC results revealed that IGF2BP2 was upregulated in HNSCC tumor tissues, and the expression level was related to the T stage." (PMID 32391379, 2020). "IHC staining of the excised tumor sections showed that the expression of Ki-67, which was consistent with that of IGF2BP2 and MYC, decreased with the depletion of LINRIS." (PMID 31791342, 2019). "Studies have shown that IGF2BP2 is overexpressed and promotes tumor progression in a variety of cancers, such as glioblastomas multiforme and gallbladder cancer." (PMID 31852504, 2019). "The insulin-like growth factor 2 (IGF2) mRNA binding protein IMP2 (IGF2BP2) is an oncogenic protein known to be overexpressed in different tumor types." (PMID 31261900, 2019). "IHC analysis showed that the expression of both SOX2 and IGF2BP2 was significantly increased in CRC tumor tissues compared with that in the paired adjacent normal tissues." (PMID 31230592, 2019). "The abnormal overexpression of IGF2BP2 is proposed to be partly due to genomic amplification and posttranscriptional regulation by tumor suppressor miRNA-141." (PMID 31852504, 2019). "a, SOX2 and IGF2BP2 IHC staining scores in primary CRC tumor tissues (T) and adjacent normal tissue (ANT) (n = 432)." (PMID 31230592, 2019). "The expression levels of anti-Let-7 target genes (in humans: HMGA2, IGF2BP2, and LIN28B; in mice: Igf2bp2, Nras, and Tgfbr1) were examined in each tumor mass and brain tissue from mice." (PMID 27102443, 2016). "In turn, over-expression of Lin28b, IGF2BP2, and IGF2 in patients’ tumours at the time of diagnosis was all associated with a higher risk of relapse." (PMID 23482325, 2012). "Additionally, FTO-driven m6A modification of circGDI2 increased its expression, whereas silencing FTO suppressed HCC tumor growth and decreased circGDI2, IGF2BP2, and PKM2." (PMID 41439029, 2026). "While insulin-like growth factor 2 mRNA-binding protein 2 (IGF2BP2) has been extensively studied in tumor cells, its role in immune cells within the tumor microenvironment, particularly in macrophages, remains largely unknown." (PMID 41943844, 2026). "Meanwhile, IGF2BP2 overexpression further increased the number of Ki-67 positive cells, indicating that IGF2BP2 reversed the inhibitory effects of silencing circGDI2 on tumor proliferation." (PMID 41439029, 2026). "In xenograft models, the impaired tumor growth induced by IGF2BP2 inhibition could be reinstated by si-STAT1." (PMID 41522349, 2026). "Finally, we constructed a nude mouse xenograft tumor model using MDA‐MB‐231 cells infected with sh‐IGF2BP2 and reported that low expression of IGF2BP2 resulted in decreases in tumor volume and weight (p < 0.05)." (PMID 39969065, 2025).
tumor (continued). "To further evaluate the therapeutic potential of IGF2BP2 inhibition, we examined whether C4 treatment reduced tumor development in PLK1-high xenograft and PDX models of TNBC." (PMID 40347943, 2025). "We observed that IGF2BP2 knockdown alone attenuates tumour growth and reduced tumour volumes." (PMID 41399129, 2025). "One study found that IGF2BP2 may work to promote tumor growth in PTC via interactions with APOE mRNA and the IL-6/JAK2/STAT3 pathway." (PMID 40243425, 2025). "The higher expression levels in the tumour of IGF2BP2 and PLAU were validated by qRT-PCR." (PMID 40762677, 2025). "Notably, both HNRNPC and IGF2BP2 promote tumor aerobic glycolysis, and our GSEA revealed that EFTUD2 upregulation was significantly and positively correlated with glycolysis." (PMID 40236649, 2025). "Importantly, WTAP upregulates PD-L1 expression through m6A-dependent mechanisms in the tumor immune microenvironment, while IGF2BP2 stabilizes the methylated PD-L1 transcript, reinforcing its accumulation and immunosuppression." (PMID 40986143, 2025). "Altering IGF2BP2 expression prevents tumor cell proliferation and resensitizes the cells to ADT." (PMID 39948708, 2025). "This could be attributed to the fact that knockdown of IGF2BP2 alone already resulted in a significant reduction in tumor volume." (PMID 39799112, 2025). "Moreover, higher IGF2BP2 expression was observed in poorly differentiated tumor and lymph node metastasis." (PMID 40362183, 2025). "↓ brain metastasis and tumor growth in vivo via PCAT6/IGF2BP2/IGF1R pathway." (PMID 41157107, 2025). "Notably, this lactate–IGF2BP2–Nrf2 axis also promoted M2 macrophage polarisation, fostering an immunosuppressive tumour microenvironment (TME)." (PMID 41399129, 2025). "Taken together, pharmacological depletion of lactate using DCA could effectively inhibit CRC tumour growth by disrupting the lactate–H3K18la–IGF2BP2–Nrf2 signalling axis." (PMID 41399129, 2025). "Our findings suggest that targeting the piR-31115/METTL3/YAP1/IGF2BP2 signalling pathway may offer a promising strategy for inhibiting tumour angiogenesis in TNBC." (PMID 39820521, 2025). "Moreover, the subcutaneous tumour transplant model further verified that IGF2BP2 knockdown decreased the growth of OVCAR3 xenografts in vivo." (PMID 40629911, 2025). "Its tumor size and mass were also significantly lower in IGF2BP2 knockdown group." (PMID 37983610, 2024). "In CRC and HCC, both benzamide benzoic acid and urea-thiophene compounds could inhibit tumor growth by downregulating IGF2BP2." (PMID 39033180, 2024). "In contrast, the overexpression of IGF2BP2 impaired the ability of IR to inhibit tumor growth." (PMID 38281999, 2024). "Utilizing gene expression analysis and various experimental models, the study confirms IGF2BP2’s role in tumorigenesis and identifies two classes of compounds, benzamidobenzoic acid and ureidothiophene, which effectively reduce tumor growth in zebrafish embryos." (PMID 39456596, 2024). "Furthermore, MeRIP-seq data showed that IGF2BP2 downregulation remarkably elevated m6A levels of spondin 2 (Spon2) and reduced mRNA levels of Spon2 in tumor tissues from A549 tumor-bearing mice." (PMID 39731162, 2024). "Consistent with the oncogenic and pro-angiogenic role of TRPM2-AS in GBC cells, RT-qPCR, western blot, and immunohistochemistry also showed that the expression level of IGF2BP2 was increased in tumor tissues, especially in those with high microvascular density." (PMID 38532427, 2024). "So, targeting and inhibiting IGF2BP2 expression could therefore suppress tumor metastasis, offering a promising strategy for slowing cancer progression." (PMID 39596216, 2024). "Enhanced glycolysis was the additional energy source for tumor proliferation and progression, for example, IGF2BP2 performed as a RBP and could regulate the m6A manner of MYC and thus promoted the aerobic glycolysis, migration and proliferation in CESC." (PMID 38383371, 2024).